RNU6-967P (RNA, U6 small nuclear 967, pseudogene)
Gene: Small nuclear RNA gene on chromosome 19 (31,787,148 to 31,787,255, reverse strand). Ensembl gene ENSG00000201894.
Homologues: Orthologues: chimpanzee U6 (100% identical), macaque U6 (93% identical), dog RNU6-967P (80% identical). Paralogues in human: RNU6-207P (81% identical), RNU6-20P (80% identical), RNU6-333P (80% identical), RNU6-1145P (79% identical), RNU6-1271P (79% identical), RNU6-128P (79% identical), RNU6-1316P (79% identical), RNU6-38P (79% identical), RNU6-1091P (78% identical), RNU6-209P (78% identical), RNU6-211P (78% identical), RNU6-214P (78% identical), and 1289 more.